LINC01960 (long independently transcribed non-coding RNA 1960)
Gene: Long non-coding RNA gene on chromosome 2 (174,025,280 to 174,027,163, forward strand). Ensembl gene ENSG00000260868.
Diseases named in the same sentence as LINC01960 in open-access papers:
LINC01960 is named in the same sentence as 1 disease in open-access papers, as found by Europe PMC text mining. Sharing a sentence is not in itself a finding about the gene and the disease. The quoted sentences say what the papers report.
endometriosis (1 paper, 2025). The growth of functional endometrial tissue in anatomic sites outside the uterine body. "A transcriptomic analysis revealed key miRNAs and lnCRNA implicated in endometriosis and RIF, including miR-9, miR-34, and miR-135a/b miR-30d-5p, PART1, MIR17HG, H19, LINC00173, NEAT1, and LINC01960-201." (PMID 39858500, 2025).